IL13 (interleukin 13)
Diseases named in the same sentence as IL13 in open-access papers (continued):
Sharing a sentence is not in itself a finding about the gene and the disease.
Tumor Lysis Syndrome (1 paper, 2021). a group of metabolic abnormalities that can occur as a complication during the treatment of cancer, most commonly after the treatment of lymphomas and leukemias. "However, there were still 4 out 18 patients showing grade 3 CRS, which might be attributed to tumor lysis syndrome and other cytokines that were significantly elevated during CART therapy, which might involve GM-CSF, G-CSF, MCP-1, TNFA, MIP-1, IL8, IL13, and IL10." (PMID 34518515, 2021).
type IV hypersensitivity reaction (1 paper, 2025). "A type IV hypersensitivity reaction, Th2-mediated and driven by interleukin-4 (IL-4), IL-5 and IL-13, promoting IgE production by B cells and activating eosinophils and mast cells, has been suggested." (PMID 40371306, 2025).
Ureteral obstruction (1 paper, 2016). Obstruction of the flow of urine through the ureter. "Three days after ureteral obstruction, we intravenously transferred M0, M (IFNγ + LPS) or M (IL4 + IL13) and assessed the degree of inflammation and fibrosis 4 days later, as displayed in the experimental design." (PMID 27621813, 2016).
vaginal disorder (1 paper, 2018). A non-neoplastic or neoplastic disorder that affects the vagina. "Since IL5 and IL13 are strongly influenced by the alteration of eubiotic conditions, regardless of the specific pathogens causing the alteration of vaginal milieu, they could be further studied as indirect markers of vaginal disorder." (PMID 29396486, 2018).
vascular dementia (1 paper, 2021). A degenerative vascular disorder affecting the brain. "Interaction between vascular dementia status and systemic infection was seen for IL-13 and IL-1β (as shown by one-way ANOVA) and in addition, GM-CSF and IL-8." (PMID 33723589, 2021). "In contrast, IL-13 and IL-1β levels were lower in vascular dementia patients with than without infection." (PMID 33723589, 2021).
Vestibular schwannoma (1 paper, 2024). A vestibular schwannoma (also known as acoustic neuroma, acoustic neurinoma, or acoustic neurilemoma) is a benign, usually slow-growing tumor that develops from the VIIIth cranial nerve supplying the inner ear. "In addition, the levels of proinflammatory/proallergic cytokines (IL-4, IL-5, IL-10, and IL-13) were higher in the macula, ampulla, and endolymphatic sac dissected from patients with MD than in the specimens from patients with vestibular schwannoma." (PMID 38595846, 2024).
viral meningitis (1 paper, 2019). Inflammation of the membranes surrounding the brain and spinal cord due to a viral infection. "In fact, it has been demonstrated that an IL-13 pathway activation is related to high CHI3L1 levels with differential patterns in bacterial or viral meningitis, suggesting the involvement of CHI3L1 in heterogeneous inflammatory pathways." (PMID 31608004, 2019).
whipworm infections (1 paper, 2019). "Although a role of IL-22 in inducing goblet cell hyperplasia and promoting microbiota homeostasis during whipworm infections cannot be excluded, the induction of this mechanism of worm expulsion in the T. muris model is strongly dependent on the actions of IL-13 and regulated by IL-10." (PMID 30640950, 2019).
xerostomia (1 paper, 2023). Dryness of the mouth resulting from reduced salivary secretion. "Among the inflammatory cytokines assessed - IL-6, TNF-α, IFN-γ, IL-10, IL-12p70, IL-1β, IL-8, IL-13, IL-2, IL-5, IL-7 and IL-17A, xerostomia correlated with lower levels of saliva IL-2 and TNF-α, and elevated levels of serum IL-12p70 and IL-10 (p < 0.05)." (PMID 36846089, 2023).
Zinc deficiency (1 paper, 2010). A deficiency of the essential metal Zinc; an essential cofactor for many enzymes. "Overall, zinc deficiency was associated with increased supernatant concentrations of TNF and IFN-γ (by 37% and 74%, respectively), and seemed associated with increased concentrations of IL-5 and IL-13." (PMID 20546583, 2010).
tumor (878 papers, 2002 to 2026). "M2-like tumor-associated macrophages (TAMs), which are abundant in MF lesions, secrete high levels of IL-4, IL-13, and TGF-β." (PMID 40864740, 2025). "In contrast, IL‐10 and IL‐13, which are associated with the suppression of anti‐tumor immune function, showed statistically significant decreases." (PMID 39815665, 2025). "Th2 polarization in the tumor microenvironment has been implicated in tumor-promoting processes mediated by IL-4 and IL-13 signaling, which enhance immune evasion, tissue remodeling, and lymphangiogenesis through M2-like macrophage activation." (PMID 41383514, 2025). "IL13 has been implicated in indirect immunosuppression through the promotion of tumor-associated macrophage (TAM) differentiation, leading to TGF-β secretion and the establishment of a tumor-promoting microenvironment." (PMID 40312750, 2025). "In lung and renal cancers, elevated IL-4/IL-13 levels are linked to increased tumor growth, metastatic potential, and poor clinical outcomes." (PMID 40497988, 2025). "IL-4 and IL-13 are the major cytokines transforming the tumor-associated macrophages (TAMs) to M2 macrophages that promote cancer progression and treatment resistance, and dupilumab reduces the pro-tumor phenotype of M2 macrophages." (PMID 39758935, 2025). "Higher levels of serum IL13 were associated with high tumor grade (P = 0.031), and higher serum IL33 levels were associated with younger age (P = 0.013)." (PMID 40928327, 2025). "The effects of IL-4, IL-13, and IL-17A on tumor immunity are controversial, as various studies have shown they are associated with tumor progression or tumor suppression." (PMID 39743545, 2025). "For example, IL-13 signaling via the IL-13Rα2 receptor has been implicated in tumor progression in some models." (PMID 40981274, 2025). "Histologically, the presence of goblet cells in the mucosal epithelium of the upper airway is closely associated with the production of cytokines such as IL‐13, IL‐8, and IL‐9, which play a role in inflammatory pathways and consequently tumor progression." (PMID 40867038, 2025). "In GCs, elevated IL-33 and IL-13 levels have been linked to enhanced tumor-associated macrophage activation, which promotes immune evasion." (PMID 40761291, 2025). "In contrast, M2 polarization, induced by cytokines of the type 2 immune response, such as interleukin (IL)-13 and IL-4, has been associated with tissue repair and tumor-promotion." (PMID 38426089, 2024). "Tregs in the tumor produce cytokines such as IL-4, IL-10, and IL-13, which cause monocytes to differentiate into tumor-associated macrophages (TAMs)." (PMID 39253716, 2024). "Although we were unable to identify the mechanism(s) underlying the upregulation of Dectin-1 in myeloid and tumor cells, it is reported that macrophages treated with IL-4 and IL-13 upregulate the expression of Dectin-1." (PMID 38668817, 2024). "In previous studies, IL13 effectively targeted the IL13 receptor on tumor cells when it was linked directly (IL13-Pseudomonas exotoxin A) or via a linker (diphtheria toxin-IL13) to a toxin." (PMID 39118800, 2024). "IL-13 has also been implicated in cancer invasion and progression by paracrine and autocrine signaling in the tumor microenvironment." (PMID 39272892, 2024). "Studies have indicated that it is associated with high expression of TGF-β, IL-4, IL-13, and IL-10, suppressing the inflammatory response and encouraging tumor angiogenesis and distant metastasis." (PMID 39108265, 2024). "Tumor-associated macrophages are often polarized to the M2-like type in response to IL-4, IL-10, IL-13, and other cytokines, favoring angiogenesis, dissemination, and immunosuppression." (PMID 39456647, 2024). "IL-4, IL-5, and IL-13 are associated with the Th2 immune response, which can create an immunosuppressive environment that promotes tumor progression." (PMID 39456897, 2024).
tumor (continued). "Conversely, activation of STAT3 and STAT6 by IL-4 and IL-13 predominantly leads to polarization of macrophages towards the M2 phenotype, associated with immune suppression and tumor progression." (PMID 38745331, 2024). "M2 macrophages, as the primary expression form of tumor-associated macrophages, promote Th2 cell differentiation through the induction of IL-4, IL-13, and other cytokines and secrete IL-10, TGF-β to suppress inflammatory cytokines." (PMID 39104717, 2024). "Tregs within the tumor can produce cytokines such as IL-4, IL-10, and IL-13, causing monocytes to differentiate into tumor-associated macrophages (TAMs)." (PMID 39253716, 2024). "All IL13(E12Y)-CAR T cell variants showed some level of tumor killing at this low E:T ratio of 1:20, suggesting their capacity to recursively kill." (PMID 36968221, 2023). "Cytokines frequently associated with tumor inflammation include interleukin (IL)-13, IL-10, transforming growth factor (TGF)-β, and IL-5." (PMID 37958472, 2023). "In the context of malignancies, IL-4 and IL-13 have been shown to induce polarization towards protumoral tumor-associated macrophages (TAM)." (PMID 38074683, 2023). "In the case of HL, IL-13 has been linked to the tumor microenvironment and interplay between tumor cells and immune system cells." (PMID 37958472, 2023). "Some studies have confirmed that Th2 cells expressing IL-13, IL-5, and IL-4 recruit M2-like tumor-associated macrophages and contribute to tumor angiogenesis by activating STAT-646–49." (PMID 37248248, 2023). "The expression of two of these ATG genes, i.e., RPN2 and TRAF5 and additionally IL-13 correlate with the mutation burden of the tumor." (PMID 36835075, 2023). "With regard to PC, Th2 cells release IL-5 and IL-13 to elevate extracellular matrix deposition and affect the development of M2 macrophages to promote fibrosis of tumor tissue which is the main causes of drug delivery difficulties as well as immunosuppression." (PMID 37371833, 2023). "Tumor-associated macrophages (TAMs) are among these immune subtypes and can be polarized to M2 by IL-13, IL-4, TGF-β, or IL-10, within the TME." (PMID 36860731, 2023). "Th2 cells can secrete multiple cytokines, such as IL-4, IL-5, IL-10, and IL-13, which are associated with inflammation and tumor-promoting functions." (PMID 36193495, 2022). "M2 macrophages are classically stimulated by cytokines IL-4, IL-13, IL-10, and M-CSF and are associated with reduction of inflammatory signals, resolution of the immune response, wound healing, and tumor promotion." (PMID 35264604, 2022). "Tumor-specific Th2 cell responses are associated with tumor immune evasion, and Th2 cytokines such as IL-4 and IL-13 are implicated in the suppression of host immune effector responses to tumors." (PMID 36105094, 2022). "IL-33 deficiency or blockade led to reduced tumour Il4, Il6 and Il13 expression, and correlated with reduced tumour mast cells." (PMID 36263033, 2022). "For example, cytokines in the TME, such as TNF-α, IL-6, and IL-8, are associated with angiogenesis and tumor metastasis, whereas IL-4, IL-13, and IL-10 are associated with immune response suppression." (PMID 35844605, 2022). "We also found that knocking out ALKBH5 activates the immune system with more antitumor-associated cytokines (IFN-γ, IL-2) and fewer pro-tumor-associated cytokines (IL-10, IL-13)." (PMID 36566230, 2022). "Tumor-associated macrophages (TAMs) are shaped by chemokines such as IL-4, IL-10, and IL-13 to suppress antitumor immunity." (PMID 35493518, 2022). "IL-4, IL-10, and IL-13 signaling, along with significantly elevated tumor-associated transcription factor abnormalities, upregulation of IL-17 and Hif-1a pathways, and glucose metabolism pathway, was enriched in Mac3, which pointed to M2 characteristics." (PMID 35874770, 2022).
tumor (continued). "Subsequently, the tumor-associated macrophages (TAMs) promote angiogenesis, tumor progression, metastasis, and resistance to chemotherapy under the influence of IL-4, IL-10, or IL-13." (PMID 36295075, 2022). "The number of tumor-infiltrating Tr1 cells (CD4+ FoxP3- IL-13- IL-10+) was associated with tumor-infiltrating pDCs, which enhanced Tr1-produced IL-10 via ICOS-L when exposed to tumor-derived factors." (PMID 35619702, 2022). "IL-13 is involved in inhibition of inflammatory cytokines, up-regulation of tumor associated macrophages (TAM), and myeloid derived suppressor cells (MDSC) without affecting activated T cells." (PMID 35062739, 2022). "M2 type TAM secrete IL-10 and IL-13, and they are associated with killing and encapsulation of parasites, Th2 activation, tissue remodeling, and tumor induction and growth." (PMID 36293435, 2022). "When macrophages are exposed to T helper 2 (Th2) cytokines (such as IL-4 and IL-13), they polarize into M2 macrophages and promote tumor growth, while tumor-associated macrophages (TAMs) are mainly characterized by M2 macrophages." (PMID 35601497, 2022). "IL-13 signaling in CRC has been associated with a poor prognosis, ILC2-derived IL-13 activates MDSCs, which promote pro-tumor TME response." (PMID 35008550, 2021). "In brief, the shift from a Th1 to a Th2 inflammatory response will lead to an increase in immunosuppressive cytokine release (IL-2, IL-4, IL-7, IL-13, and IL-15) by neoplastic elements and tumor-associated cells, sustaining tumor growth and spread." (PMID 34685762, 2021). "IL-4 and IL-13 are also involved in the crosstalk with the tumor microenvironment (TME) by activating tumor-associated macrophages and myeloid-derived suppressor cells, which have tumor promoting functions." (PMID 33450900, 2021). "Th2 cells were suggested to play a central role in the development of primary tumors and metastases by secreting cytokines such as IL-4 and IL-13 that induce a tumor-promoting M2 or M2-like phenotype of tumor associated macrophages." (PMID 34868011, 2021). "For example, it was shown that TNFR1 signaling promotes the accumulation of anti-tumor M1 polarized tumor-associated macrophages (TAMs) by suppressing the M2-polarizing release of IL-13 from eosinophils co-recruited with inflammatory monocytes." (PMID 34445397, 2021). "Both IL-4 and IL-13 are involved in the differentiation of macrophages into pro-tumorigenic M2, which are classified as tumor-associated macrophages (TAMs)." (PMID 34071442, 2021). "IL-13 has been shown to activate tumor associated macrophages which in turn promote tumor cell metastasis and survival, indicating its potential as a therapeutic target." (PMID 33008336, 2020). "Tumor-associated macrophages can be stimulated by IL-4, IL-10, or IL-13 and then migrate into tumor tissue, where they perform protumorigenic functions." (PMID 33292489, 2020). "With respect to T cell-associated cytokines, TH2 cytokines (like IL-4, IL-5 and IL-13) were selectively elevated in tumor patients suggesting an immunosuppressed status in these patients." (PMID 30740106, 2019). "Cancer stem cells located towards the periphery of the primary tumour appear to secrete a number of molecules (e.g. Interleukin-13, -34 and oesteoactivin) that recruit monocytes and cause them to differentiate into Tumour-Associated Macrophages (TAMs)." (PMID 30819129, 2019). "Expression of Il4, Il10 and Il13, which represent cytokines commonly associated with alternative macrophage activation, was undetectable in 4T1 tumours." (PMID 30054470, 2018). "IL-4 and IL-13 were key players for activating tumor-associated macrophages and myeloid-derived suppressor cells that promoted tumor development." (PMID 30486830, 2018). "These activated ILC2s promoted monocytic myeloid-derived suppressor cell (M-MDSC) activation through IL-13 secretion and were associated with poorer tumor control." (PMID 30454038, 2018).
tumor (continued). "Many studies have revealed that expression level of IL-13 is elevated in various tumor tissues and peripheral blood, which is associated with poor outcome and involved in tumor progression." (PMID 30643796, 2018). "Improved survival in iNKT-cell-deficient mice was associated with increased production of IFN-γ, while tumor growth in WT mice correlated with higher IL-13 production." (PMID 29375569, 2017). "In contrast, exposure to IL-4 and/or IL13 (24h) polarizes them towards pro-tumor M2-macrophage fate (aka tumor associated macrophages or TAMs), as detected by increased expression of the M2-macrophage biomarkers; CCL17 and CCL18 in them (see RT/PCR analysis)." (PMID 29262555, 2017). "The preferential production of IL-13, a cytokine implicated in promoting tumor growth, by LPC specific type II NKT cells suggests their role in disease progression." (PMID 29018445, 2017). "As expected, NF-κB activation (as assessed by measuring IκB-α phosphorylation and expression levels of the representative Th2 cytokines IL-4 and IL-13) was significantly downregulated in sST2-expressing tumours compared with sST2-deficient tumours." (PMID 27882929, 2016). "Macrophages, an important cell component of the tumor stroma, are recruited and mobilized by tumor-derived factors such as IL-4, IFN-γ and IL-13 and then induced to differentiate into pro-tumorigenic tumor-associated macrophages (TAMs)." (PMID 27367025, 2016). "Further, M2-like polarized tumor-associated macrophages (TAMs), which can be induced by IL-13, promote EMT and cancer metastasis." (PMID 27533463, 2016). "Intriguingly, IL-13 has also been reported to activate tumor-associated macrophages (TAMs), which promotes proliferation, survival and metastasis of tumor cells." (PMID 27533463, 2016). "Results demonstrated that densities of CD68 and IL-13 in tumor stroma area were probably associated with the prognosis of patients." (PMID 26771842, 2016). "Reports in the literature associated IL-13 with inhibition of tumor proliferation, by increasing antigen presentation to T cells." (PMID 26347589, 2015). "IL-13 and IL-4 modify the function of macrophages, and IL13RA2 mediates IL13/4 mediated tumor associated macrophage M1/M2-Th1/Th2 phenotype, especially, IL-13 signaling promote to change M1 to M2." (PMID 26114873, 2015). "Similarly, Ovatodiolide inhibits the expression of YAP-regulated M2 tumor-associated macrophage polarization factors, such as IL-4 and IL-13, altering the tumor microenvironment and thereby regulating the progression of CRC." (PMID 40612350, 2025). "IL-4/IL-13 blockade has been linked to reduced tumor progression in various tumor models." (PMID 40843371, 2025). "Moreover, tumor-associated macrophages protect tumor cells by an IL-13/IL-4-mediated increase of miR-660-5p, which was packed into exosomes and transferred to tumor cells." (PMID 39372215, 2024). "Through our integrated clinical-biomarker–immunologic analyses derived from a diverse, pan-tumor cohort, we found that early increases in Th17 (IL-6, IL-17f), type 2 (IL-5, IL-13, IL-25), and type 1 (TNF-α) cytokines were associated with the development of grade ≥ 2 irAEs." (PMID 39403935, 2024). "IL-4, in association with IL-13, promotes tumor cell growth and proliferation in CTCL." (PMID 38607023, 2024). "In turn, TAMs may motivate the self-renewal and tumorigenic capacity of TCSCs, Using IL-4 and IL-13 cytokines, macrophages were successfully polarized towards M2-like tumor-associated macrophages (M2-like TAMs) in a co-culture experiment." (PMID 39776907, 2024). "IL‐13 is associated with cellular immunity to tumor formation." (PMID 36806727, 2023). "In addition, high IL-13 levels were closely associated with a high level of Tregs in the tumor microenvironment." (PMID 37534250, 2023). "While antitumor efficacy could be seen in mice treated with each of the variants, the most significant effects on tumor burden and overall survival were observed with the IL13-BBζ CAR T cells." (PMID 36968221, 2023).